PLSCR1 (phospholipid scramblase 1)
Diseases named in the same sentence as PLSCR1 in open-access papers (continued):
Sharing a sentence is not in itself a finding about the gene and the disease.
Cerebral ischemia (2 papers, 2020). Restriction of arterial blood supply to the brain associated with insufficient oxygenation to support the metabolic requirements of the tissue. "The two main findings of the present study are that TRPC5 physically associates with PLSCR1 to facilitate PS externalization in HEK293 cells and mouse cerebral neurons, and that inhibiting TRPC5 may have a protective effect in cerebral ischemia-reperfusion injury." (PMID 32110987, 2020). "In a very recent study, TRPC5 was found to directly interact with phospholipid scramblase 1 (PLSCR1) on the plasma membrane to facilitate externalization of phosphatidylserine (PS) and apoptosis of cortical neurons in response to cerebral ischemia/reperfusion." (PMID 33490083, 2020).
cervical cancer (2 papers, 2022 to 2025). A primary or metastatic malignant neoplasm involving the cervix. "Treatment of HeLa cervical cancer cells with RSV reduced viability and proliferation was correlated with the downregulation of phospholipid scramblase 1 (PLSCR1)." (PMID 36558430, 2022).
epidermoid carcinoma (2 papers, 2012 to 2020). "PLSCR1 has also been reported to interact with EGFR in EGF-stimulated epidermoid carcinoma cells." (PMID 32292520, 2020).
granulomatosis with polyangiitis (2 papers, 2018 to 2022). A small-vessel necrotizing vasculitis characterized by the association of inflammation of the vessel wall and peri- and extravascular granulomatosis. "PLSCR1 pro-inflammatory properties have also been involved in granulomatosis with polyangiitis (GPA; formerly known as Wegener’s granulomatosis), a rare chronic, potentially fatal, autoimmune disease characterized by blood vessel inflammation and the formation of necrotizing granulomas." (PMID 35650588, 2022).
HCMV infection (2 papers, 2022). "have recently demonstrated that PLSCR1 is also implicated in the control of human cytomegalovirus (HCMV) infection." (PMID 35650588, 2022). "The expression pattern of PLSCR1 induced by HCMV infection differs in human embryonic lung and OUMS-36T-3 cells." (PMID 35138119, 2022). "Next, we determined the HCMV infection-mediated induction of PLSCR1 expression in HEL and 36T-3 cells." (PMID 35138119, 2022). "In addition, the basal expression of MxA in 36T-3 cells was also higher than that in HEL cells, and HCMV infection decreased the levels of PLSCR1 and MxA at up to 5 h p.i.." (PMID 35138119, 2022). "To confirm this PLSCR1-mediated repression of HCMV MIE gene expression, we next evaluated the expression levels of the 72-kDa protein IE1 (UL123), which is one of the proteins encoded by the MIE genes, in HEL, 36T-3, and PLS1KO-A cells after HCMV infection by immunoblot analysis." (PMID 35138119, 2022). "In particular, the interaction between PLSCR1 and CREB was found to be critical for blocking HCMV infection, given the central role of this nuclear factor in the activation of viral transcription through the major immediate early promoter." (PMID 35650588, 2022). "In addition, compared to that in PLSCR1-KO cells, the expression of major immediate early (MIE) proteins is repressed and/or delayed in parental 36T-3 cells after HCMV infection." (PMID 35138119, 2022). "Furthermore, compared to that in PLSCR1-KO cells, the expression of HCMV major immediate early (MIE) proteins was repressed and/or delayed in parental 36T-3 cells after HCMV infection." (PMID 35138119, 2022). "In HEL cells, the basal expression of PLSCR1 was significantly lower in the absence of HCMV infection." (PMID 35138119, 2022). "Interestingly, the basal expression of PLSCR1 in 36T-3 cells was significantly higher than that in HEL cells in the absence of HCMV infection." (PMID 35138119, 2022).
HIV-1 infection (2 papers, 2009 to 2023). The type species of lentivirus and the etiologic agent of acquired immunodeficiency syndrome (AIDS). "Since SLPI was able to disrupt the association between PLSCR1 and CD4, our data suggest that SLPI inhibits HIV-1 infection by modulating the interaction of the CD4 receptor with PLSCRs." (PMID 19333378, 2009).
idiopathic inflammatory myopathies (2 papers, 2022 to 2023). "PLSCR1 shows increased expression in multiple systemic AIDs, such as primary antiphospholipid syndrome, rheumatoid arthritis, idiopathic inflammatory myopathies, and SLE." (PMID 37313407, 2023). "Ultimately, PLSCR1 has been found an increased expression in multiple systemic autoimmune diseases, such as primary antiphospholipid syndrome, rheumatoid arthritis, idiopathic inflammatory myopathies and SLE." (PMID 35757721, 2022).
liver cancer (2 papers, 2022). An epithelial or non-epithelial malignant neoplasm that arises from the liver. "recently demonstrated that PLSCR1 expression is up-regulated in primary liver cancer and is associated with the clinical stage and hepatitis B virus (HBV) infection." (PMID 35650588, 2022). "Silencing PLSCR1 using siRNA in hepatic cancer (LoVo) cells inhibit their proliferation, adhesion, migration and invasion suggesting PLSCR1 to be a key regulatory protein that contributes to the malignancy of liver cancer cells." (PMID 35422844, 2022). "PLSCR1 knockdown significantly inhibited the proliferation, adhesion, migration and invasion of cancer cells, suggesting that PLSCR1 might be a suitable therapeutic target in regimens aimed at preventing the progression of primary liver cancers." (PMID 35650588, 2022).
mantle cell lymphoma (2 papers, 2016 to 2022). Mantle cell lymphoma is a rare form of malignant non-Hodgkin lymphoma affecting B lymphocytes in the lymph nodes in a region called the ``mantle zone''. "PLSCR1 negatively regulates the protective autophagy in mantle cell lymphoma (MCL) induced by 9-cis-retinoic acid (RA)/Interferon (IFN)-α (RA/IFNα)." (PMID 35422844, 2022).
psoriasis (2 papers, 2022 to 2023). An autoimmune condition characterized by red, well-delineated plaques with silvery scales that are usually on the extensor surfaces and scalp. "PLSCR1 was shown to play an important role in the interleukin (IL)-36/interferon-I axis contributing to psoriasis." (PMID 37035327, 2023). "A previous RNA-seq analysis of whole blood from psoriasis patients implicated the pDC-mediated release of IFN-α after induction by IL-36 in a TLR-9-dependent manner, evidenced by the upregulation of PLSCR1 in pDCs." (PMID 35563374, 2022). "The expression levels of phospholipid scramblase 1 (PLSCR1), heme binding protein 1 (HEBP1), structural maintenance of chromosomes 4 (SMC4), and RuvB like AAA ATPase 1 (RUVBL1) genes were shown to be reversed by candidate compounds for psoriasis using the RORUCI values." (PMID 37035327, 2023).
anaphylaxis (1 paper, 2017). An acute hypersensitivity reaction that occurs from exposure to an allergen. "This was accompanied by a reduced anaphylactic reaction (i.e. reduced drop in body temperature) showing that PLSCR1 controls the severity of anaphylaxis." (PMID 28282470, 2017).
asthma (1 paper, 2023). "Overall, our studies demonstrated that PLSCR1 played an essential role in the pathogenesis of ILC2 responses, providing critical insights into biology and disease pathogenesis and identifying targets that can be manipulated in attempts to control IT2IR in chronic diseases such as asthma." (PMID 37289545, 2023).
Buruli ulcer (1 paper, 2020). "Thus, PLSCR1 may be an interesting candidate gene for involvement in the development of Buruli ulcer." (PMID 32313116, 2020).
colon adenocarcinoma (1 paper, 2012). "PLSCR1 was highly expressed in colon adenocarcinoma, medullary thyroid carcinoma, and transitional bladder carcinomas." (PMID 23259795, 2012).
glaucoma (1 paper, 2025). Increased pressure in the eyeball due to obstruction of the outflow of aqueous humor. "While PLSCR1 has been implicated in apoptotic pathways in other diseases, such as glaucoma, its potential role in virus-induced apoptosis remains largely unaddressed." (PMID 40248364, 2025).
lung carcinoma (1 paper, 2025). "PLSCR1 is an interferon-inducible (IFN) gene that is localized to lipid rafts; the loss of PLSCR1 using an shRNA-based approach led to a loss of cellular protection to the virulence factor, α-toxin, which is derived from Staphylococcus aureus, in A549 lung cancer cells." (PMID 40004137, 2025).
nasopharyngeal carcinoma (1 paper, 2025). A carcinoma arising from the nasopharyngeal epithelium. "In another study by Kusano and Ikeda, PLSCR1 was implicated in EBV infection, as it interacts with EBV protein BZLF1 and represses BZLF1-mediated lytic gene transcription in EBV-infected nasopharyngeal carcinoma (NPC)." (PMID 40248364, 2025).
neutropenia (1 paper, 2017). A decrease in the number of neutrophils found in the blood. "However, a transient neutropenia in the newborn Plscr1-/- mice was reported that was related to a defect in stress granulopoiesis ("emergency granulopoiesis") due to a decreased response to G-CSF." (PMID 28282470, 2017).
pneumonia (1 paper, 2008). An acute, acute and chronic, or chronic inflammation focally or diffusely affecting the lung parenchyma, caused by an infection in one or both of the lungs (by bacteria, viruses, fungi, or mycoplasma.). "Of interest, the RNA abundance of five genes were altered by pneumonia in both the mouse and human gene sets: lactotransferrin (LTF), cathelicidin antimicrobial peptide (CAMP), phospholipid scramblase 1 (PLSCR1), inhibin beta A (INHBA), and hydroxyprostaglandin dehydrogenase 15-(NAD) (HPGD)." (PMID 18270561, 2008).
thrombosis (1 paper, 2024). "PLSCR1 and IKZF3 are associated with SLE thrombosis and disease risk." (PMID 39845969, 2024).
infection (15 papers, 2018 to 2025). The state of being infected such as from the introduction of a foreign agent such as serum, vaccine, antigenic substance or organism. "Plscr1-/- mice exhibited significantly greater weight loss compared to WT mice with both sublethal and lethal dose infection at multiple time points." (PMID 41439508, 2025). "Recent SARS-CoV-2 variants showed reduced differences in infection rates between PLSCR1 WT and KO cells than the parental SARS-CoV-2 strain." (PMID 39316623, 2024). "Likewise, engineered loss of Plscr1 rendered mouse LET1 cells more permissive to infection by intact mouse coronavirus (MHV), which belongs to the same β-coronavirus genus as the SARS-CoV-2, SARS-CoV, MERS-CoV and BatCoV-WIV-1 strains." (PMID 37438530, 2023). "Taken together, these observations strongly suggest that PLSCR1 expression may affect susceptibility to infection through several mechanisms depending on the virus, the host cell type, and/or the interacting protein." (PMID 35650588, 2022). "We found significantly elevated levels of Ifna, Ifnb, Ifng, and Ifnl expression in Plscr1-/- mice, particularly in early infection." (PMID 41439508, 2025). "Significantly higher Plscr1 expression was observed in WT infected mice at 3 days post-infection (dpi), suggesting that Plscr1 is induced and potentially functions as an antiviral ISG in IAV infection in vivo." (PMID 41439508, 2025). "As a widely expressed ISG, PLSCR1 interacts with inflammatory proteins, cell-death related proteins, and membrane receptors to modulate host hemostasis in infections." (PMID 40248364, 2025). "Massive dsRNA foci were observed in 60% of PLSCR1-KO cells by 180 min after infection, when viral release has occurred, but the production of new virions has not been completed." (PMID 37438530, 2023). "PLSCR1-enriched foci were observed as early as 30 min after infection, which completely overlapped viral particles detected by anti-spike or anti-nucleocapsid antibodies." (PMID 37438530, 2023). "Here, measuring the total viral RNA levels using quantitative PCR (qPCR) showed that infection by both VOCs increased significantly by 6.0-fold (Delta) or 7.6-fold (Omicron) in PLSCR1-KO cells." (PMID 37438530, 2023). "The results show that PLSCR1 expression is markedly decreased when examined at 1 day post infection (dpi)." (PMID 35595813, 2022). "We then used 103 pfu H1N1 SIV to infect C57BL/6 J mice intranasally and examined PLSCR1 levels at different time points post infection." (PMID 35595813, 2022). "We established Plscr1-/- mice and found them more susceptible to IAV (WSN) compared to WT mice, as evidenced by greater weight loss in both sublethal and lethal infection and poorer survival in a lethal infection." (PMID 41439508, 2025). "(A–E) Wild-type (WT) and Plscr1-/- mice were exposed to sublethal (300 pfu) IAV (WSN) infection." (PMID 41439508, 2025). "Notably, while differences in viral copy numbers were only observed at the early stages of infection, coinciding with a significant increase in Plscr1 transcription, these changes had profound implications for host fitness." (PMID 41439508, 2025). "SRP68 and PLSCR1 implicate ongoing cellular adjustments in response to infection stress." (PMID 38655085, 2024). "At 6 h post infection (p.i.), cell lysates were immunoprecipitated with a rabbit pAb against PLSCR1, followed by western blotting with a rabbit anti-PLSCR1 pAb for the detection of PLSCR1 and a mouse anti-NP mAb to reveal the presence of NP." (PMID 29352288, 2018). "These pro-viral effects highlight the complexity of PLSCR1’s interactions with different viruses and suggest that its role may be context-dependent, shaped by the specific cellular and molecular environments during infection." (PMID 40248364, 2025). "Importantly, since IFN-α production by Plscr1-/- pDCs was impaired in infection not only with HSV (a DNA virus), but also with IAV (an RNA virus), both TLR9 and TLR7 pathways might be affected." (PMID 40248364, 2025).
infection (continued). "Multiple host restriction factors, such as transport protein particle complex 6A (TRAPPC6A), phospholipid scramblase 1 (PLSCR1), free fatty acid receptor 2 (FFAR2), inhibit IAV replication at various infection stages through such interactions." (PMID 41463543, 2025). "As a type 1 transmembrane protein highly expressed in the lungs following infection, ILDR1 promotes SIV replication by inhibiting the PLSCR1-NP interaction." (PMID 40248364, 2025). "Mutating all five cysteine residues to alanine (labelled 5CA) completely abolished the localization of PLSCR1 to the plasma membrane and SARS-CoV-2-containing vesicles after infection." (PMID 37438530, 2023). "The upregulation of IFITM3, STAT1, STAT2, PLSCR1, and NMI after infection was validated using western blotting and qRT-PCR." (PMID 34818332, 2021). "In contrast, neither colocalization nor clear expression of Plscr1 or Ifn-λr1 was evident without infection, implying an infection-specific interaction in human airway epithelial cells." (PMID 41439508, 2025). "Moreover, upon infection with a 900 pfu lethal dose of IAV, Plscr1-/- mice had a significantly lower survival rate." (PMID 41439508, 2025). "As a result, downregulation of PLSCR1 expression inhibited HCV entry and infection." (PMID 35650588, 2022). "As a result, downregulation of PLSCR1 expression inhibits HCV entry and infection." (PMID 29352288, 2018). "However, we did not observe any significant difference in PLSCR1 levels before and post-infection in macrophages and neutrophils, the two immune populations that express IFN-λR1 besides dendritic cells." (PMID 41439508, 2025). "PLSCR1(5CA) also did not protect against infection when reintroduced into PLSCR1-KO cells." (PMID 37438530, 2023).
tumor (15 papers, 2012 to 2025). "The BLBC subtype is usually associated with large tumor size, high grade, metastasis, early recurrence, and poor survival, and high-level expression of PLSCR1, contributing to enhanced STAT1 activation, was found to promote cancer stem cell properties." (PMID 35650588, 2022). "Despite extensive studies, little is known about the functions and underlying mechanisms of PLSCR1 in tumor progression." (PMID 32292520, 2020). "PLSCR1 has been implicated in maintaining plasma membrane lipid asymmetry, regulating growth factor signaling pathways, in modulating tumor growth in mouse xenograft models, and cancer development." (PMID 23621864, 2013). "In recent years, accumulating evidence has revealed that PLSCR1 is not only involved in apoptotic signaling, but also participates in a wide range of biological processes, including tumor differentiation, interferon responses, and antiviral defense." (PMID 41146421, 2025). "The sensitivity and/or proliferative capacity of tumor cells can also be affected by phospholipid scramblase 1 (PLSCR1) which is involved in several processes including phosphatidylserine exposure on an apoptotic cell surface." (PMID 37239828, 2023). "Midkine, a heparin-binding growth factor that plays pivotal role in tumorigenesis and tumor progression is localized to nucleus and interacts with PLSCR1." (PMID 35422844, 2022). "Tumor from PLSCR1-transfected cancer cells were greatly reduced in size, showed increased infiltration of leukocytes and macrophages and differentiated into spindle shaped morphology." (PMID 35422844, 2022). "Conversely, silencing IFIT3 and PLSCR1 genes in tumor cells can negatively affect the internalization of vesicular stomatitis and Newcastle disease viruses." (PMID 34771433, 2021). "Western blotting analysis of tumor samples showed a dramatic decrease in PLSCR1 expression when it was knocked down, which was consistent with the results in cell lines, showing similar inhibitory effects in vitro and in vivo." (PMID 32292520, 2020). "The knockdown of PLSCR1 led to significant inhibitory effects on proliferation, migration, invasion, tumor growth and lung metastasis of BLBC cells." (PMID 32292520, 2020). "Markedly, MDA-MB231 cells with knockdown of stable PLSCR1 expression led to reduced tumor growth in vivo." (PMID 32292520, 2020). "Emerging evidence has suggested that phospholipid scramblase 1 (PLSCR1) is involved in tumor progression." (PMID 32292520, 2020). "The anti-tumor effect of wogonoside was related to cell cycle arrest and differentiation via inhibition of PLSCR1 (phospholipid scramblase 1) expression and regulation of subcellular localization in the nucleus." (PMID 31070530, 2018). "The relatively broad range of percentages of PLSCR1 positive cells observed is consistent with an evident intra-tumor and inter-patient heterogeneity." (PMID 27248824, 2016). "Despite progress in this area of PLSCR1-related biological function, with few exceptions little is known about the roles of PLSCR1 in the control of tumor cell proliferation or transformation." (PMID 23259795, 2012). "Additionally, PLSCR1 is thought to be involved in tumour proliferation because its overexpression has been observed as part of EGF stimulation pathways." (PMID 38391955, 2024). "Collectively, these findings suggest that the pro- or anti-tumor properties of PLSCR1 may depend on the intracellular locations of PLSCR1 and its interactors." (PMID 35650588, 2022). "Over expression of PLSCR1 suppress growth of malignant tumor in athymic nude mice." (PMID 35422844, 2022). "Furthermore, our study elucidates a critical mechanism of how PLSCR1 is transported to the nucleus and contributes to tumor progression in BLBC." (PMID 32292520, 2020). "Our results rather suggest that PLSCR1 expression could be correlated to a decreased propensity of tumor cells to undergo autophagy." (PMID 27248824, 2016).